KIT (KIT proto-oncogene, receptor tyrosine kinase)
Diseases named in the same sentence as KIT in open-access papers (continued):
Sharing a sentence is not in itself a finding about the gene and the disease.
gastrointestinal stromal tumor (continued). "Based on these findings, KIT-negative gastrointestinal stromal tumor (GIST) was suspected." (PMID 37902858, 2023). "The immunohistochemically detectable expression of receptor tyrosine kinase (KIT) [cluster of differentiation (CD) 117] and discovered on gastrointestinal stromal tumors protein (DOG) 1 is pathognomonic for over 95% of all GIST." (PMID 36188659, 2022). "Imatinib (brand name Gleevec) is a kinase inhibitor acting against Abelson tyrosine kinase BCR–ABL, the KIT and PDGF receptors and is used for therapy of chronic myeloid leukemia (CML), gastrointestinal stromal tumors (GIST) and several other malignancies." (PMID 34409045, 2021). "For example, imatinib and sunitinib, which are used on gastrointestinal stromal tumours (GISTs), simultaneously interrupt BCR-ABL, KIT, and PDGFR tyrosine kinase pathways, promoting cell cycle arrest; sorafenib inhibits the VEGFR, PDGFR, KIT, FLT3, and RAF pathways in late-stage kidney cancer." (PMID 26312766, 2015). "Aberrations in KIT expression and signaling, including over-expression or reduced/absent expression, have been characterized in several tumors, such as gastrointestinal stromal tumors, breast cancer, and thyroid carcinoma, but the role of KIT in human neoplasia is not fully cleared understood." (PMID 26581891, 2015). "Imatinib was also found to inhibit both wild type c-KIT and mutant c-KIT that is often found in gastrointestinal stromal tumor (GIST) and was approved to treat the disease." (PMID 24926233, 2014). "Furthermore we evaluated the gene expression of KIT as well as the alternative RTK FLT3, CSF1-R, PDGFRB, AXL and MET in mutated and non-mutated gastrointestinal stromal tumors by qPCR using the identified reference genes." (PMID 21171987, 2010). "as KIT tyrosine kinase inhibitor (TKI) is an accepted treatment of chronic eosinophilic leukemia, hypereosinophilic syndrome, chronic myeloid leukemia, myelodysplastic/myeloproliferate syndrome, acute lymphoblastic leukemia, dermatofibrosarcoma protuberans, gastrointestinal stromal tumors." (PMID 19811659, 2009). "Synovial sarcomas, myxoid/round-cell liposarcomas, and gastrointestinal stromal tumors clustered tightly within the former cluster and discriminatory signatures for these were characterized by developmental genes from the EGFR, FGFR, Wnt, Notch, Hedgehog, RAR and KIT signaling pathways." (PMID 17359542, 2007). "Positive immunoreactivity of a subset of spindle cells for KIT suggested a diagnosis of gastrointestinal stromal tumor (GIST), although DOG1 was negative." (PMID 41897612, 2026). "Avapritinib, a potent inhibitor of KIT and platelet-derived growth factor receptor A (PDGFRA) tyrosine kinases, has demonstrated unprecedented clinical activity in PDGFRA D842V-mutant gastrointestinal stromal tumors (GIST)." (PMID 33740926, 2021). "Recently, we reported that KIT, a type III RTK, accumulates in intracellular compartments, such as endosomal/lysosomal membrane and the Golgi apparatus, in mast cell leukemia (MCL), gastrointestinal stromal tumor (GIST), and AML21–24." (PMID 34811450, 2021). "c-KIT overexpression is well recognized in numerous malignancies, including SCLC, as well as melanoma, non-small-cell lung cancer (NSCLC), acute myelogenous leukemia (AML), and gastrointestinal stromal tumors (GIST)." (PMID 31484422, 2019). "About 10-15% of adult gastrointestinal stromal tumors (GIST) and the vast majority of pediatric GIST do not harbour KIT or platelet-derived growth factor receptor alpha (PDGFRA) mutations." (PMID 25239601, 2014). "Immunohistochemical staining differentiates leiomyomas from gastrointestinal stromal tumors (GISTs), with leiomyomas expressing desmin and smooth muscle actin (SMA) but lacking CD34 and KIT." (PMID 40177232, 2025).
gastrointestinal stromal tumor (continued). "Immunohistochemical (IHC) staining was critical for differentiation from malignant gastrointestinal stromal tumors (GISTs), as leiomyomas were consistently positive for desmin and smooth muscle actin (SMA) but negative for CD34 and KIT." (PMID 40177232, 2025). "Unlike gastrointestinal stromal tumors (GISTs), which benefit from molecular characterization and targeted therapies, LMS lacks KIT and DOG1 expression and typically follows a more aggressive course with limited systemic treatment options." (PMID 41281033, 2025). "A gastrointestinal stromal tumor (GIST), the most common mesenchymal neoplasm of the gastrointestinal tract, originates from interstitial cells of Cajal (ICC) or related mesenchymal progenitors that require an elevated KIT expression for lineage specification and survival." (PMID 37108337, 2023). "About 10-15% of adult gastrointestinal stromal tumors (GIST) and the vast majority of pediatric GIST do not harbour KIT or platelet-derived growth factor receptor alpha (PDGFRA) mutations (J Clin Oncol 22:3813–3825, 2004; Hematol Oncol Clin North Am 23:15–34, 2009)." (PMID 25239601, 2014). "We present for the first time a malignant gastrointestinal stromal tumor of the gallbladder, immunoreactive for platelet-derived growth factor receptor alpha (PDGFRA) and negative for CD 117 antigen (c-KIT)." (PMID 21760661, 2011). "DOG1 and PKCθ are overexpressed in KIT-negative gastrointestinal stromal tumors, indicating that DOG1 and/or PKCθ may be used in the diagnosis of KIT-negative GISTs." (PMID 36358843, 2022). "Gastrointestinal stromal tumors (GISTs) represent the majority of primary non-epithelial neoplasms of the digestive tract, most frequently expressing the KIT protein detected by the immunohistochemical staining for the CD117 antigen." (PMID 18294396, 2008). "Gastrointestinal stromal tumors (GISTs), which may also display spindle cell morphology, can be differentiated through the absence of endothelial markers and the positive staining for CD117 (c-KIT), which is typically absent in angiosarcoma." (PMID 40710858, 2025). "In most gastrointestinal stromal tumors (GISTs), genetic alterations of KIT or platelet-derived growth factor A (PDGFRA) gene that activate their functions are detected, while wild-type GIST, in which these genetic alterations are not detected, accounts for approximately 10% of all GISTs." (PMID 31974683, 2020).
melanoma (689 papers, 2000 to 2026). A malignant, usually aggressive tumor composed of atypical, neoplastic melanocytes. "The KIT inhibitors can only exert their effect in a particular subtype with KIT amplification and specific mutation in melanoma." (PMID 39744440, 2025). "Treatment sequencing in KIT-mutant melanoma should be guided by mutation class, therapeutic response patterns, and disease distribution." (PMID 41301010, 2025). "There is also a “rule of thumb” in melanoma, i.e., only one oncogene can be mutated in the same pathway, meaning that these three mutations (KIT/NRAS/BRAF) are mutually exclusive." (PMID 40361349, 2025). "While the prevalence of KIT mutations remains low in the overall melanoma population, their consistent enrichment in specific histologic subtypes and well-defined molecular mechanisms of action have made them an important biomarker subgroup." (PMID 41301010, 2025). "For instance, mutations in the BRAF, NRAS, and KIT genes are well-documented in human melanomas, leading to constitutive activation of the MAPK pathways promoting tumorigenesis." (PMID 41394861, 2025). "(2005) showed that acral melanomas often have distinct genetic alterations compared to other melanoma subtypes, including a higher prevalence of KIT mutations (15%–20% of cases) and a lower frequency of BRAF mutations (less than 5%)." (PMID 41164124, 2025). "KIT mutations in melanoma are most commonly localized to exons 11, 13, and 17, which encode the juxtamembrane and kinase domains of the receptor." (PMID 41301010, 2025). "In contrast, c-KIT mutations are more frequently observed in mucosal melanomas, particularly in the head and neck region." (PMID 40003600, 2025). "The response to imatinib in melanoma patients depends on the type of KIT mutation, with certain exon mutations correlating with better treatment responses." (PMID 40331942, 2025). "Most recently in 2024, the multicenter, single-arm NICAM phase II trial evaluated nilotinib in 26 KIT-mutated melanoma patients (AM n = 6)." (PMID 39858514, 2025). "Scientists sometimes distinguish the KIT Proto-Oncogene (KIT) melanoma subtype, which is primarily associated with acral and mucosal melanomas and is more prevalent in Asian populations." (PMID 40867277, 2025). "In this review, we summarize the associations between KIT mutations and specific clinico-pathologic patterns, including their enrichment in acral, mucosal, and chronically sun-damaged melanomas." (PMID 41301010, 2025). "Some articles also pointed out that c-KIT is an oncogenic driver in many cancers, and its mutations and amplifications are crucial to the progress in melanoma 25, 37-39." (PMID 39744440, 2025). "Targeting MEK is currently the most developed targeted strategy in NRAS-mutated melanoma while KIT inhibitors are approved for KIT-mutated cases specifically." (PMID 40331942, 2025). "Exon 13, part of the kinase domain I, harbors the K642E mutation, observed in 10 to 15% of KIT-mutant melanoma cases." (PMID 41301010, 2025). "This growing list of mutations illustrates the genetic heterogeneity of KIT-mutant melanoma and underscores the utility of comprehensive sequencing, particularly in cases with unclear clinical features or resistance to standard therapies." (PMID 41301010, 2025). "In melanoma, imatinib has shown modest but clinically meaningful efficacy in specific biologically distinct subtypes characterized by KIT mutations or amplifications, including acral, mucosal, and chronically sun-damaged melanomas." (PMID 41302945, 2025). "These mutations have created possible targets for therapy such as Tyrosine kinase inhibitors that have potential in KIT-mutated melanomas." (PMID 41164124, 2025). "KIT mutations, related to specific subtypes of human melanomas, have also been reported in canine melanomas." (PMID 41394861, 2025). "Acral melanomas exhibit KIT mutations in 8.3–23% of cases, while mucosal melanomas have the highest reported frequency, ranging from 15.6% to 50%." (PMID 40508177, 2025).
melanoma (continued). "Previous studies have demonstrated that approximately 25% of patients with KIT-mutant melanoma present with a de novo missense mutation in exon 17, many of which are resistant to currently available TKIs." (PMID 41301010, 2025). "With an overall response rate (ORR) ranging from 16 to 29%, it was discovered that imatinib effectively treated melanoma patients who had KIT amplification and/or mutations in phase II clinical studies." (PMID 40429850, 2025). "The molecular spectrum of KIT mutations in melanoma is defined by a set of recurrent activating alterations that cluster within specific domains of the KIT receptor tyrosine kinase." (PMID 41301010, 2025). "Nilotinib is a more potent second-generation TKI demonstrating potential promise for KIT-mutated melanoma." (PMID 39858514, 2025). "KIT mutations occur in approximately 10–20% of these melanoma subtypes, with a notable incidence of 10.8% in a study of 502 cases." (PMID 40867277, 2025). "The mutational spectrum of KIT in melanoma includes alterations across several exons, with classic activating mutations in particular that predict sensitivity to KIT inhibitors in select patients." (PMID 41301010, 2025). "Although present in only about 3% of all melanomas, KIT mutations are disproportionately found in tumors arising from acral sites, mucosal surfaces, and chronically sun-damaged skin." (PMID 41301010, 2025). "Only four patients with advanced melanoma were tested for KIT mutations, with one of them resulting positive for mutation E554K." (PMID 40994966, 2025). "In select subtypes such as acral and mucosal melanomas, KIT mutations can guide off-label use of KIT inhibitors." (PMID 40981345, 2025). "Mutations in the KIT gene are more frequently observed in mucosal, acral, and chronically sun-damaged melanomas, leading to sustained activation of the KIT receptor and promoting tumor cell proliferation and survival." (PMID 41346595, 2025). "Overall, KIT mutations are a critical factor in the prognosis and treatment strategies for specific melanoma subtypes." (PMID 40867277, 2025). "In terms of anatomical distribution, KIT mutations are enriched in melanomas that arise in mucosal tissues (e.g., oral, genital, and anal surfaces) and acral locations (e.g., palms, soles, and subungual areas)." (PMID 41301010, 2025). "Together, L576P and K642E account for over half of all KIT mutations in melanoma and have become prototypical examples of “hotspot” mutations." (PMID 41301010, 2025). "For example, some have BRAF mutations, which are often the classic V600E gain-of-function (GOF) mutation that is seen frequently in melanoma and other cancer types, and this is often mutually exclusive with KIT/PDGFRA mutations." (PMID 38730662, 2024). "KIT mutations: For melanomas with KIT mutations, tyrosine kinase inhibitors such as imatinib and nilotinib are viable therapeutic options." (PMID 39859956, 2024). "A phase 2 trial is underway in Japan to evaluate the efficacy of imatinib in combination with pembrolizumab in patients with KIT‐mutated melanoma, and the results are awaited." (PMID 38087810, 2024). "Tyrosine kinase inhibitors, such as imatinib, have shown efficacy in treating melanomas with activating KIT mutations, providing a tailored therapeutic approach for these patients." (PMID 39200315, 2024). "Though the rate of BRAF mutations is low in mucosal melanomas, the rate of c-KIT mutation is often higher than is present in traditional cutaneous melanoma." (PMID 39001457, 2024). "The ongoing research and development of treatments targeting c-KIT mutations are pivotal in enhancing care and outcomes for patients with these specific melanoma subtypes." (PMID 38474231, 2024).
melanoma (continued). "A phase II study found that the ORR for patients with melanoma harboring mutated KIT and treated with a specific treatment targeting this mutation (e.g., imatinib) was 23%." (PMID 38539487, 2024). "KIT mutations are other frequently mutated genes in melanoma and offer another potential target for therapy." (PMID 39199633, 2024). "Activating KIT mutations are found in 20–90% of mucosal (anorectal and oral cavity) melanomas, approximately 36% of acral melanomas (AM), and approximately 28% of high-CSD cutaneous melanomas." (PMID 38247727, 2024). "In our c-KIT mutated cohort we bring the first series of older melanoma patients treated with imatinib, which shows encouraging results in terms of RR, especially given that all patients received treatment as a 2nd or 3rd line following ICI." (PMID 39207855, 2024). "Favorable outcomes have been reported in patients with KIT-mutated rectal melanoma, and, in some cases, complete remission has been achieved in patients with KIT-mutated melanoma following treatment with sunitinib." (PMID 39449907, 2024). "Case 61 had an NRASG12C mutation in the invasive portion and a metastasis, whereas the melanoma in situ instead had separate amplifications involving KIT and CRKL, both being known driver mutations of acral melanoma." (PMID 39034322, 2024). "While not explicitly approved for melanoma, its effectiveness in a subset of melanoma patients underscores the potential of targeting KIT mutations in this cancer type." (PMID 39199633, 2024). "These rare melanomas have a mutation in a gene called KIT, and this gene abnormality was also found in the DNA that circulates in plasma." (PMID 38417447, 2024). "NGS is also utilized in select cases where KIT mutations are suspected (ie, acral or mucosal melanomas)." (PMID 39661469, 2024). "Perhaps KIT mutation exposes this dilemma in our understanding of the origin and nature of melanoma when it concerns the melanoma subtypes." (PMID 38539487, 2024). "This type of melanoma rarely presents mutations in the BRAF and NRAS genes, common in other melanomas, but has a high frequency of mutations in the KIT gene, which can activate the MAPK signaling pathway." (PMID 39202970, 2024). "Although the results are not as pronounced as those with BRAF and MEK inhibitors, these treatments have shown efficacy in melanomas with KIT mutations." (PMID 39859956, 2024). "This review explores the intricate interplay between genetic alterations, such as mutations in BRAF, NRAS, and KIT, and melanoma pathogenesis." (PMID 39200315, 2024). "Mutations in the KIT gene are particularly significant in specific melanoma subtypes, such as acral lentiginous melanomas and mucosal melanomas." (PMID 39200315, 2024). "While KIT mutations are detected in only 3% of melanomas overall, they are notably prevalent and found in approximately 35% of acral and mucosal melanomas." (PMID 38891988, 2024). "In a study involving 90 patients with stage III or IV acral, mucosal, or cumulative sun-damaged skin melanoma, 11% of the melanomas tested had mutations in KIT." (PMID 39200315, 2024). "Clinical benefits from c-KIT inhibitors have been observed in selected patients, underscoring the importance of these mutations in the therapeutic landscape of melanoma." (PMID 38474231, 2024). "In melanoma, KIT mutations show heterogeneous distribution through the gene, and they are detected most frequently in exon 11 (L576P) and exon 13 (K642E)." (PMID 37372988, 2023). "A number of melanoma recurrent mutations have been reported in the literature in several genes including KIT, TERT, MAP2K1 and MAP2K2, RAC and PPP6C." (PMID 36765773, 2023). "St.rikingly, some observations uncovered that Sprout-related EVH1 domain-containing protein 1 (SPRED1) loss promotes cell proliferation in KIT-driven melanoma, as a result of SPRED1's function as a tumor suppressor in the MAPK pathway." (PMID 37773078, 2023).